RNU6-14P (RNA, U6 small nuclear 14, pseudogene)
Synonyms: RNU6-14
Gene: Small nuclear RNA gene on chromosome 9 (15,776,181 to 15,776,286, reverse strand). Ensembl gene ENSG00000207360.
Homologues: Orthologues: tropical clawed frog U6 (94% identical), dog U6 (86% identical). Paralogues in human: RNU6-1 (97% identical), RNU6-2 (97% identical), RNU6-3P (97% identical), RNU6-4P (97% identical), RNU6-5P (97% identical), RNU6-6P (97% identical), RNU6-9 (97% identical), RNU6-12P (96% identical), RNU6-13P (96% identical), RNU6-16P (96% identical), RNU6-17P (96% identical), RNU6-18P (96% identical), and 1285 more.